TNF (tumor necrosis factor)
Diseases named in the same sentence as TNF in open-access papers (continued):
Sharing a sentence is not in itself a finding about the gene and the disease.
tumor (continued). "Of note, IL-12 is essential for NK cell activation and production of tumour necrosis factor-alpha (TNF-α) and IFN-γ, as well as for the subsequent activation of anti-tumour immune responses, given that NK cells are the principal innate effector cells that express potent anti-tumour immunity." (PMID 32931721, 2020). "Furthermore, TNFα increases liver metastasis through inducing expression of cell adhesion molecules, such as ICAM-1, E-selectin and VCAM-1, on liver specific endothelial cells, and thus enhancing tumor cell arrest and transendothelial migration." (PMID 33339340, 2020). "Therefore, lowering the threshold of TNF-induced death in tumours, through the targeting of cIAPs (together or not with TRAF2, another death-limiting factor), enhances ICI efficiency." (PMID 32365592, 2020). "However, STING signaling in macrophages did not result in production of TNFα, demonstrating the differential response in tumor cells and macrophages." (PMID 33202881, 2020). "Tumor-derived microvesicles obtained from colorectal cancer cells promote the differentiation of blood monocytes into macrophages with mixed features of M1/M2 polarization, induce phosphorylation of STAT1 and STAT3 and change the secretion of cytokines such as IL-10, IL-12 and TNF." (PMID 32488850, 2020). "In addition, Th9 CAR-T cells secreted lower amounts of IL2 and TNF-α than Th1 CAR-T cells, but Tc9 CAR-T cells secreted significantly higher levels of IL2 and TNF-α than Tc1 CAR-T cells, especially after coculture with tumor cells." (PMID 33214555, 2020). "Furthermore, while birinapant did not increase TNF secretion by CLs, it did sensitize the tumor cells to TNF induced death." (PMID 32053868, 2020). "Meanwhile, the stronger capability to secrete PRF and TNF-α rather than GZMB through MHC class II molecules might be responsible for the anti-tumor activity of CD8+PD-1+CD161+ T cells." (PMID 33145436, 2020). "In contrast, dying tumor cells can stimulate the production of TNF-α, epidermal growth factor (EGF), IL-6, and Wnt ligands, which in turn recruit myeloid cells and fibroblasts to the local TME, serving as anti-cell death signals and decreasing the efficacy of anti-tumor therapies." (PMID 32973519, 2020). "However, it was also shown that the pro-tumor TAN N2 subset exhibits the ability to suppress the proliferation of intratumor CD8+ T cells and their IFNγ production and to induce CD8+ T cell apoptosis by secretion of TNFα and NO." (PMID 33505304, 2020). "Administration of both anti-TNF-α and an IL1-receptor antagonists in models of cancer cachexia also shows evidence of preservation of body weight and improved food intake compared to untreated tumor-bearing controls, suggesting a common mechanism for both cytokines." (PMID 33329046, 2020). "Besides, expression of S100A8/A9 in endothelial cells and myeloid in premetastatic organs in response to transforming growth factor β, tumor necrosis factor α (TNFα), and VEGF expressed by distal primary tumors promotes homing of tumor cells to premetastatic niches." (PMID 33117687, 2020). "Significant and selective TNF-α expression within the tumor without detectable serum levels could be demonstrated in three different tumor models." (PMID 32917034, 2020). "Tumor cells compete with T cells for nutrients in the TME due to their similar metabolic processes, resulting in compromised T-cell receptor (TCR) signaling and dampened production of cytokines such as interferon-γ (IFN-γ), interleukin-2 (IL-2), and tumor necrosis factor-α (TNF-α)." (PMID 32424240, 2020). "Using a xenograft model of human melanoma, it was shown that tumour-specific T cells expressing a hybrid molecule containing the TIGIT extracellular domain fused to the CD28 intracellular domain displayed enhanced production of IFN-γ and TNF-α and improved tumour control." (PMID 32708397, 2020). "Similarly, TNFα, RIP1, c-FLIP, and FADD may serve important roles in contributing to SM resistance in tumor cell lines." (PMID 32325691, 2020).
tumor (continued). "Furthermore, these EVs possessed a molecular profile similar to the pro-tumor, immunosuppressive phenotype observed in TAMs, which includes increased expression of M2 markers (CD163 and CD206) and reduced expression of M1 markers (IRF5 and TNF-a)." (PMID 33143238, 2020). "In addition, dysregulation of TNF-α production can induce expression of matrix metalloproteinase-9 (MMP-9), which is an enzyme involved in degradation of extracellular matrix and promotion of tumor metastasis." (PMID 32595759, 2020). "Moreover, prophylactic TNF blockade does not hinder, but rather enhances, the anti-tumor effect of anti-CTLA-4 and anti-PD-1 combination treatment." (PMID 31974523, 2020). "In contrast to TNF, which induces apoptosis both in cancer and healthy cells and thereby its administration in cancer patients causes unacceptable systemic toxicity, TRAIL selectively affects tumor cell survival without harming healthy cells." (PMID 33287223, 2020). "The expression of TNF-α, IL-1α, and IL-6 from MDA-MB-231 cells was shown to be inhibited by apigenin, and the inhibition of TNF-α-induced CCL2 release by apigenin was thought to suppress tumor migration and metastasis through the regulation of tumor microenvironment." (PMID 31252615, 2019). "Furthermore, TNFα upregulation by monocytes could in turn promote the release of the monocyte and macrophage chemoattractant MCP-1 by monocytes and a range of tumour cell types." (PMID 31544825, 2019). "Therefore, ECM targeting of TNFα, in contrast to unconjugated TNFα, attracts T cells into the tumour microenvironment irrespective of tissue phenotypes, without inducing systemic toxicity." (PMID 31709774, 2019). "Therefore, it is foreseeable that an unbalance in TNF production could skew MDSC toward an inflammatory, anti-tumor phenotype." (PMID 31281314, 2019). "The TNF-SF system gained attention again when non-toxic and tumour cell-selective killing could be observed using TRAIL instead." (PMID 30935038, 2019). "Such dramatic changes in tumor cell physiology might be a consequence of NF-κB activation in iCCA and might be induced upon exposure to TNFα, where stimulation leads to increased matrix metalloproteinase (MMP9) expression, an essential enzyme for tumor invasion and metastases." (PMID 31349670, 2019). "Notably, tumor-induced osteoclastogenesis targeting OPCs was resistant to denosumab, infliximab, and osteoprotegerin (OPG) in contrast to positive controls, in which OPCs were also treated with RANKL or TNF-α." (PMID 31835378, 2019). "Finally, whether in patients with maximum tumor size ≤ 5 cm or >5 cm, high preoperative serum IL6, IL8, and TNF-α levels were distinctly correlated with shorter RFS." (PMID 31781194, 2019). "As expected, the tumor-bearing DCs co-cultured with cryo-thermal macrophages were highly matured, as demonstrated by the increased percentage of CD11c+CD86+MHC II+ DCs along with the higher relative expression of IL-6, TNF-α, CXCL10, IL-1β, IL-12p40, and IL-15 mRNA." (PMID 30833570, 2019). "Hypoxic tumor cells secrete angiogenic cytokines, such as vascular endothelial growth factor (VEGF), platelet-derived growth factor (PDGF) and basic fibroblast growth factor (bFGF) that stimulate neovascular formation and inflammatory cytokine, such as TNF-α and IL-1β." (PMID 31653130, 2019). "Accordingly, TNFR2 blockade should be evaluated in future experimental studies as potentially new therapeutic approach that might reduce nephrotoxicity without affecting systemic and anti-tumor effects of CDDP-induced TNF-α." (PMID 30866950, 2019). "Importantly, the blockade of TNF resulted in an improvement of tumor survival in DSS-treated tumor-bearing mice after ICB therapy, unlike IL-6 neutralization, which harmed rather than improved ICB-enhanced anti-tumor responses." (PMID 31309173, 2019).
tumor (continued). "Furthermore, we noted that the levels of activated N1-ICD were much increased in MDA-MB-231:MSC “Contact” co-cultures compared to those of the tumor cells or MSCs when grown individually; the high N1-ICD levels in “Contact” co-cultures were slightly elevated by TNFα stimulation." (PMID 31105691, 2019). "Further exploration in tumor immune microenvironment revealed that the abundance of TIL increased, the expression of negative co-stimulatory molecules (PD-1/Lag-3/Tim-3) decreased, and the secretion of pro-inflammation cytokines (IFN-γ and TNF-α) elevated after Olaparib administration." (PMID 31521196, 2019). "Interestingly, poly A:U decreased by half the density of M2-like macrophages producing IL10 inside the tumor bed, and at the same time expanded the number of monocyte-derived cells producing TNF, particularly among those that did not express MHCII." (PMID 30949170, 2019). "Therefore, in the tumor inflammatory microenvironment, ionizing radiation effects on NRP1 may regulate IL-17, TNF, IL-6, IL-8 and other inflammatory factors to enhance the radiation resistance of A549 cells." (PMID 31417646, 2019). "However, in TNFα-stimulated co-cultures, p65-regulated CXCL8 expression was partially contributed by MSCs, even though most of the p65-induced CXCL8 expression was contributed by the tumor cells (Figure 3B2)." (PMID 31105691, 2019). "Our observations also indicate that when the tumor cells and the stromal cells did not form physical contacts but exchanged soluble factors, TNFα stimulation gave rise to production of soluble factors; it is possible that these factors, together with TNFα itself have directly activated p65." (PMID 31105691, 2019). "Additionally, these compounds showed immunomodulatory and tumor growth inhibition effects by increasing the phagocytic activity of macrophages, the proliferation of splenocytes, and the levels of NK-cell activity, IFN-γ, and TNF-α." (PMID 30925876, 2019). "It has been reported that fucoidan can be used as an adjuvant by inducing the up-regulation of CD40, CD80 and CD86 expression and production of interleukin-6 (IL-6), IL-12 and tumor necrosis factor-α (TNF-α) in spleen cDCs, which may have an effect on the development of tumor vaccines." (PMID 30897733, 2019). "The results showed that TNF-α could significantly enhance the tumor sphere formation ability of control cell lines but not in the anti-miR-497 group, indicating that TNF-α improves HCC self-renewal specifically depending on miR-497." (PMID 31650028, 2019). "It is known that the TNF works as an anti-tumor cytokine, while its role may be negatively converted to be a tumor-promoting substance upon its conjugation with TNFR2, which is only expressed on some tumor cells and immunosuppressive cells." (PMID 31877663, 2019). "However, TNFα‐CSG treatment and adoptive transfer of both CD8+ and CD4+ T cells (triple combination) produced anti‐tumour effects similar to those observed in syngeneic 4T1 tumour‐bearing mice." (PMID 31709774, 2019). "IL-10 and TGF-β reduce synthesis of interferon-gamma (IFN-γ) and TNF-α by pro-inflammatory CD4 T cells, thus, lower tumor-specific cytotoxicity of CD8 cells, inhibit the main functions of dendritic cells and NK cells and this way induce tolerance to tumor cells." (PMID 31717542, 2019). "Moreover, the apoptosis inducers TNF-α (24–72 h after SBRT), IL-1α, IL-1β, IL-6 FASL, and TGF-β were released during radiotherapy; higher levels of TNF-α agreed with the abscopal effect and complete tumor response." (PMID 31871454, 2019). "Cross-linking of IgE bound to tumour cells via the Fab region did not trigger TNFα." (PMID 31544825, 2019). "However, direct implication of TNF in tumor growth control is lacking and would require evaluation of this phenomenon upon anti-PD-1/anti-TNF combination therapy." (PMID 31417576, 2019).
tumor (continued). "Interestingly, Astragaloside III also strongly elevated the protein levels of IFN-γ, IL-12 but not TNF-a and IL-6 in tumor tissue, indicating the broad immune regulatory activities and restricted over inflammation in tumor." (PMID 31456687, 2019). "Therefore, the identification of sensitizing agents that are capable of suppressing TNF-α-induced survival signaling could be an attractive discovery in facilitating the enhancement of TNF-α-mediated apoptosis and tumor progression." (PMID 31766230, 2019). "Moreover, in the absence of TNFα stimulation, basal p65 activation mainly in the tumor cells has induced Notch1 activation (Figures 9A1,C1), which then contributed to a contact-dependent induction of CXCL8." (PMID 31105691, 2019). "Also, the activation of Tumor Necrosis Factor (TNF) family ligands that expressed on the surface of NK cells with IL-2, IL-15, IL-12, IL-18, and CD40 cytokines production induce NK cell cytotoxicity against tumor target cells and IFNγ production." (PMID 31457012, 2019). "Indeed, IL-1β, TNF-α, and IFN-γ levels decreased in tumor-bearing p2x7-/- mice whereas TGF-β increased, confirming the hypothesis that P2X7 deficiency favors immune suppression." (PMID 30655604, 2019). "Consistent with the DC maturation results, tumour-cell debris after HMME/R837@Lip-augmented SDT could act as an antigen to trigger the highest level of DC-secreted immune cytokines, such as IL-6 and TNF-α, which further demonstrated that the immune adjuvant R837 could enhance the immune response." (PMID 31048681, 2019). "Via TNF-α/nuclear factor kappa B (NF-κB) and phosphatidylinositol 3-kinase (PI3K)/AKT pathways, sotetsuflavone suppresses the migration and invasion of NSCLC cells and may be effective in treating the tumor." (PMID 31885751, 2019). "Furthermore, KLT had an inhibitory effect on tumor growth in vivo, but also had a slight inhibitory effect on tumors derived from the TNF-α group, suggesting that KLT is not effective against EMT tumors." (PMID 29467927, 2018). "However, irradiated tumor cells that showed approximately 30 to 35% of apoptosis, inhibited DCs maturation through the downregulation of MHC II and CD 86 expression as well as suppression of IL-12, TNF α and IL-6 release." (PMID 30081891, 2018). "For example, N1 neutrophils produce higher levels of TNFα, NO, and ROS, and are able to kill cancer cells whereas N2 neutrophils express high levels of C-X-C chemokine receptor type 4 (CXCR4 or CD184), gelatinase B/MMP9, among other markers, and act as mediators of tumor progression." (PMID 29719508, 2018). "Furthermore, when activated human T cells were co-cultured with PD-L1 positive human tumor cells, PD1-Fc-OX40L was observed to concentrate to the immune synapse, which enhanced proliferation of T cells and production of IL-2, IFNγ and TNFα, and led to efficient killing of tumor cells." (PMID 30563566, 2018). "Moreover, tumor tissue-derived TIM-1+B cells were potent suppressors of CD8+ T cell effector functions, as the TNF-α and IFN-γ production of CD8+ effector T cells was significantly decreased after coculture with TIM-1+ B cells or without depleting TIM-1+B cells." (PMID 30526680, 2018). "Based on the analysis of articles retrieved in the PubMed database, we found that melittin could induce apoptosis and constrain the progression of tumor cells as a result of regulating critical cancer-related signaling pathways, such as PI3K-Akt and TNF signaling pathways." (PMID 29854840, 2018). "HLA-DR+ CTLs expressed higher levels of the cytolytic proteins Granzyme B (p = 0.02) and Perforin (p = 0.03); Eomes (p = 0.03), involved in differentiation of effector CTLs and the inflammatory cytokine TNFα (p = 0.03), which also has anti-tumor properties, in comparison with HLA-DR negative CTLs." (PMID 30555458, 2018).
tumor (continued). "Moreover, it was found that ESG evidently increased the production of TNF in serum of the tumor-bearing mice but did not affect any other cytokines that are characteristic for Th1, Th2, or Th17." (PMID 30108589, 2018). "Although not shown so far for tumors, TNF-related macrophage death may represent an alternative way of how TNFR2 signaling in macrophages might contribute to tumor progression." (PMID 29892300, 2018). "Based on the literature reports and our previous findings, we therefore hypothesized that suppression of ANO1 overexpression may result in an upregulation of death receptor-ligand systems such as TNF-α signaling mediated by FADD, thus leading to suppression of tumor proliferation and metastasis." (PMID 29899325, 2018). "However, immunoblotting analysis of CRC tumor microenvironment cultures (HCT116 and HCT116R) treated with resveratrol alone or in combination with 5-FU or with TNF-β or with TNF-α showed marked suppression of vimentin, the transcription factor slug and induction of E-cadherin expression." (PMID 30002278, 2018). "In stark contrast to the pro-tumorigenic function, N1 TANs hindered tumor proliferation and metastasis via producing more superoxide and hydrogen peroxide, promoting CD8+ T cell recruitment and activation, expression of higher levels of Fas, TNF-α and ICAM-I27,37." (PMID 29930287, 2018). "In addition, NK cells produce a broad range of pro-inflammatory cytokines such as interferon (IFN) γ, Tumor necrosis factor (TNF) α and Granulocyte–macrophage colony-stimulating factor (GM-CSF), which can interfere with tumor cell proliferation or virus replication." (PMID 30292240, 2018). "Although TNF‐α treatment did not cause obvious changes in the viability and apoptosis rate of tumour cell, the overexpression of exogenous PTEN gene in tumour cell produced a reduction in the viability and an elevation in the apoptosis rate of target cell after exposed to TNF‐α treatment." (PMID 29632814, 2018). "Briefly, during the experiment, dCAR-T cells could release significant levels of cytokines only in the presence of cognate tumor cells expressing both CEA and MSLN, including 751 pg/mL IL-2, 9297 pg/mL IFNγ, 1777 pg/mL TNFα, 732 pg/mL IL-4, 8991 pg/mL IL-13, and 99 pg/mL IL-15." (PMID 30103775, 2018). "Physiologically, the inhibition of the TNF‐α/NF‐κB/CUL4B axis significantly reduced proliferation, invasion, and colony formation, induced cell cycle arrest at the S phase, and attenuated the in vivo tumor forming ability, and the overexpression of CUL4B can greatly reverse these effects." (PMID 29377600, 2018). "Interestingly, we have also described here that oleuropein alone or in combination did not modify tumor growth in this animal model and that even promotes a pro-inflammatory status increasing IL-6 and TNFα production." (PMID 29373553, 2018). "However TNF-alpha mutants have been developed that specifically bind either TNF-R1 or TNF-R2 and novel mutants have been obtained with lower toxicity and increased anti-tumor activity compared to wild type TNF-alpha." (PMID 30170620, 2018). "However, in our study, TNFα monotherapy was not very successful and led to a tumor growth delay of only 6 days, and 1 complete response that was not permanent, because the secondary challenge resulted in tumor growth." (PMID 29468364, 2018). "Our data demonstrate that chronic TGFβ imprinting in conjunction with activation and IL-2 has opposite effects of acute TGFβ exposure (6 h to 3 days), driving NK cells to produce more IFNγ and TNFα upon tumor target and PHA stimulation than NK cells that were not TGFβ imprinted." (PMID 30400618, 2018). "Th-1 lymphocytes recruited to a tumor site may be responsible for enhanced production of IFN-γ and tumor necrosis factor-α (TNF-α) which in turn stimulates CXCL10 secretion from a variety of cells helping to maintain and potentiate cytokine production in the tumor microenvironment." (PMID 29416784, 2018).